SCAF4 (SR-related CTD associated factor 4)
Description:
Anti-terminator protein required to prevent early mRNA termination during transcription. Together with SCAF8, acts by suppressing the use of early, alternative poly(A) sites, thereby preventing the accumulation of non-functional truncated proteins. Mechanistically, associates with the phosphorylated C-terminal heptapeptide repeat domain (CTD) of the largest RNA polymerase II subunit (POLR2A), and subsequently binds nascent RNA upstream of early polyadenylation sites to prevent premature mRNA transcript cleavage and polyadenylation. Independently of SCAF8, also acts as a suppressor of transcriptional readthrough.
Synonyms: KIAA1172; SFRS15; DKFZp434E098; SRA4; FZS
Tractability: PROTAC: ubiquitination databases record sites on it; its protein half-life has been measured.
Gene: Protein-coding gene on chromosome 21 (31,670,804 to 31,732,184, reverse strand). Ensembl gene ENSG00000156304.
Subcellular location: Nucleus
Subcellular location (Human Protein Atlas): Nucleoplasm
Gene Ontology:
Molecular function: RNA binding; RNA polymerase II C-terminal domain phosphoserine binding; nucleic acid binding
Biological process: negative regulation of termination of RNA polymerase II transcription, poly(A)-coupled
Cellular component: nucleoplasm; nucleus
Genetic constraint (gnomAD): Loss-of-function variants: 18 observed, 93.57 expected, observed/expected ratio (o/e) 0.19, 90% interval 0.13 to 0.28. The upper end of that interval is the gene's LOEUF score, 0.28, which puts it in group 1 of 6, group 1 being the genes least tolerant of losing a copy. Missense variants: 1,108 observed, 1,252.3 expected, observed/expected ratio (o/e) 0.88, 90% interval 0.84 to 0.93. Synonymous variants: 476 observed, 433.03 expected, observed/expected ratio (o/e) 1.1, 90% interval 1.02 to 1.19.
Gene-disease validity (ClinGen):
ClinGen rates the evidence that SCAF4 causes each of these diseases.
complex neurodevelopmental disorder (autosomal dominant): Definitive. A disorder that involves more than one phenotype associated with the central nervous system, including but not limited to intellectual disability, autism, and seizures (epilepsy).
Homologues: Orthologues: chimpanzee SCAF4 (100% identical), macaque SCAF4 (99% identical), dog SCAF4 (95% identical), pig SCAF4 (94% identical), rabbit SCAF4 (93% identical), guinea pig SCAF4 (91% identical), rat Scaf4 (90% identical), mouse Scaf4 (89% identical), tropical clawed frog scaf4 (63% identical), zebrafish scaf4a (49% identical), zebrafish scaf4b (36% identical), Drosophila melanogaster Isha (32% identical), and 1 more. Paralogues in human: SCAF8 (40% identical).
Diseases named in the same sentence as SCAF4 in open-access papers:
SCAF4 is named in the same sentence as 13 diseases in open-access papers, as found by Europe PMC text mining. Sharing a sentence is not in itself a finding about the gene and the disease. The quoted sentences say what the papers report.
esophageal cancer (2 papers, 2023 to 2025). A primary or metastatic malignant neoplasm involving the esophagus. "In another study, a subtype of signature composed of ELOA and SCAF4 was identified, and a subtype diagnostic and prognostic model was constructed for therapeutic targeting in esophageal cancer." (PMID 40149317, 2025).
autism spectrum disorder (1 paper, 2025). A spectrum of developmental disorders that includes autism, and Asperger syndrome. "Almost all patients with SCAF4 gene variants exhibit developmental delay/intellectual impairment, mainly Language development disorders, behavioral abnormalities such as autism spectrum disorders, hyperactivity, and aggressive behavior." (PMID 40290495, 2025).
developmental delays (1 paper, 2025). "More than 85% patients with SCAF4 gene variants exhibited developmental delays or intellectual impairments, with language development disorders being particularly pronounced." (PMID 40290495, 2025).
epilepsy (1 paper, 2025). A brain disorder characterized by episodes of abnormally increased neuronal discharge resulting in transient episodes of sensory or motor neurological dysfunction, or psychic dysfunction. "Clinically, managing patients with SCAF4 gene variants should include careful monitoring for multisystem involvement, with particular attention to the potential development of epilepsy." (PMID 40290495, 2025).
Fliedner-Zweier syndrome (1 paper, 2025). "Variants in the SR-related C-terminal domain-Associated factor 4 (SCAF4) gene are linked to Fliedner-Zweier syndrome (FZS), which presents with diverse symptoms, including mild intellectual disability, seizures, behavioral abnormalities, and various skeletal and structural anomalies." (PMID 40290495, 2025).
neurodevelopmental disorder (3 papers, 2022 to 2025). A behavioral and cognitive disorder with onset during the developmental period that involves impaired or aberrant development of intellectual, motor, or social functions. "Recently, variants in SCAF4 have been reported to cause a neurodevelopmental disorder (NDD) (Fliedner-Zweier syndrome, MIM#620511)." (PMID 39668183, 2025). "With detailed evaluation of clinical data, in silico predictions and structural modeling, we further characterized the molecular and clinical spectrum of the autosomal dominant SCAF4-associated neurodevelopmental disorder." (PMID 39668183, 2025). "The authors proposed that truncating or gene-disrupting variants in SCAF4 result in diverse neurodevelopmental disorders, with impaired SCAF4 function leading to altered mRNA processing and splicing." (PMID 40290495, 2025). "In summary, we identified a proband carrying a SCAF4 nonsense mutation, presenting with a neurodevelopmental disorder primarily characterized by language development delay." (PMID 40290495, 2025). "Current evidence suggests that heterozygous loss-of-function variants in SCAF4 can impair mRNA processing, leading to neurodevelopmental disorders." (PMID 40290495, 2025). "Our study confirms the role of SCAF4 variants in neurodevelopmental disorders and further delineates the associated clinical phenotype." (PMID 39668183, 2025). "SCAF4 was important for correct usage of polyA sites for mRNA termination, and might be associated with the variable neurodevelopmental disorder." (PMID 36685960, 2022). "A large number of genes were differentially expressed between the progenitors and his parents, supporting the hypothesis that nonsense mutations in SCAF4 lead to loss of function and are associated with transcriptional impairment and neurodevelopmental disorders." (PMID 40290495, 2025). "RNA sequencing from the patient demonstrated widespread transcriptional dysregulation, reinforcing the role of SCAF4 dysfunction in impaired transcription and neurodevelopmental disorders." (PMID 40290495, 2025). "With its CTD-interacting domain, SCAF4 binds to the C-terminal domain of the largest subunit of RNA polymerase II, encoded by POLR2A, another gene implicated in a neurodevelopmental disorder." (PMID 39668183, 2025). "This characterizes the SCAF4-associated phenotype as a rather mild and non-specific neurodevelopmental disorder with variable clinical expression and high, though not complete, penetrance." (PMID 39668183, 2025).
cancer (2 papers, 2025). A tumor composed of atypical neoplastic, often pleomorphic cells that invade other tissues. "Extensive in vitro and in vivo analyses demonstrated that PTf‐SRiApt preferentially suppresses the proliferation of “transcriptionally addicted” TNBC cancer cells with heightened SCAF4 and POLR2A expression." (PMID 40574704, 2025). "Based on recent studies, SCAF4 is a target and biomarker of interest in cancer." (PMID 40149317, 2025).
tumor (1 paper, 2025). "PTf‐SRiApt effectively inhibits tumor growth and induces cell cycle arrest in TNBC cells with elevated SCAF4 and POLR2A expression." (PMID 40574704, 2025).
SCAF4 also shares sentences with these, for which no sentence is quoted: amyotrophic lateral sclerosis type 1 (1 paper); Intellectual disability (1); intellectual impairments (1); pancreatic cancer (1); viral infection (1).